P2RX7 (purinergic receptor P2X 7)
Diseases named in the same sentence as P2RX7 in open-access papers (continued):
Sharing a sentence is not in itself a finding about the gene and the disease.
neuroblastoma (35 papers, 2013 to 2025). Neuroblastoma (NB) is the most common solid, extracranial childhood tumor. "Here, we demonstrated that BCI, an allosteric inhibitor of DUSP1/6 phosphatases, upregulates P2rx7 gene expression in neuroblastoma cells via p38 MAPK, adding to the factors implicated in the control of P2RX7 expression." (PMID 36589747, 2022). "The purpose of this study was to elucidate the signaling pathways underlying the transcriptional upregulation of P2rx7 gene expression in neuroblastoma cells following serum starvation." (PMID 26687764, 2015). "Interestingly, RA-induced neurite outgrowth and neuronal marker expression in neuroblastoma cells is associated with decreases in the expression and activity of P2RX7." (PMID 36589747, 2022). "P2X7 receptor (P2RX7) is expressed strongly by most human cancers, including neuroblastoma, where high levels of P2RX7 are correlated with a poor prognosis for patients." (PMID 36589747, 2022). "P2RX7 activation ultimately culminates in metabolic reprogramming, favoring the adaptation of neuroblastoma cells to adverse conditions." (PMID 36589747, 2022). "In summary, our data highlight DUSP1 as a novel negative regulator of P2RX7 expression in neuroblastoma cells due to the downregulation of the p38 pathway." (PMID 36589747, 2022). "Specificity protein 1 (Sp1) is a transcription factor that plays a crucial role in the control of P2rx7 gene expression in neuroblastoma." (PMID 36589747, 2022). "P2RX7 is expressed strongly by primary neuroblastoma cells and cell lines, and high P2RX7 expression correlates with the poor prognosis of stage IV neuroblastoma patients." (PMID 36589747, 2022). "Here, we show that BCI-dependent inhibition of DUSPs produces a potent upregulation of P2RX7 in neuroblastoma cells and that this effect is partially mediated by p38 activation." (PMID 36589747, 2022). "We previously reported that serum deprivation triggers EGFR-dependent activation of the PI3K/Akt pathway in neuroblastoma N2a cells, which is crucial for the Sp1-dependent transcription of P2rx7 gene." (PMID 36589747, 2022). "P2RX7 is expressed strongly by nearly all human cancers investigated to date, including primary neuroblastoma tumors and cell lines derived from these." (PMID 36589747, 2022). "Serum withdrawal triggers EGFR-dependent activation of the PI3K/Akt pathway in neuroblastoma cells, inducing the upregulation of P2rx7 gene expression, which in turn promotes the survival/proliferation of cancer cells in the absence of trophic support." (PMID 36589747, 2022). "As such, studies have recently shown that P2RX7 participated in tumors metastasis, and it is up-regulated compared with normal tissues, including chronic lymphocyte leukemia, melanoma, neuroblastoma, prostate, breast and thyroid cancers." (PMID 31159832, 2019). "Next, we faced the question of how PKCζ is regulating Sp1-dependent P2rx7 gene expression in neuroblastoma cells." (PMID 26687764, 2015). "Altogether, these results reveal that serum deprivation induces activation of PI3K/Akt pathway that results in Sp1-induced expression of P2rx7 gene in neuroblastoma cells." (PMID 26687764, 2015). "We previously identified Sp1 as the main nuclear factor involved in controlling P2rx7 gene expression in N2a neuroblastoma cells and here, blocking Sp1-dependent transcription with mithramycin A significantly reduced but did not abolish the expression of P2RX7 in BCI-treated cells." (PMID 36589747, 2022). "Moreover, P2RX7 activation facilitates the exocytotic release of ATP, which would activate P2RX7 in the same or neighboring neuroblastoma cells, further stimulating its own release and negatively controlling cell differentiation." (PMID 36589747, 2022). "As such, a better understanding of the intracellular signaling pathways that regulate P2RX7 expression in neuroblastoma cells could be biologically and clinically relevant." (PMID 36589747, 2022).
neuroblastoma (continued). "Consequently, an induction of P2rx7 gene expression takes place, increasing the endogenous levels of P2X7 transcript and protein in neuroblastoma cells, and allowing cell proliferation even in the absence of trophic support." (PMID 26687764, 2015). "Hence, better understanding how the levels of P2RX7 are regulated in neuroblastoma cells may lead to the development of more effective, less toxic therapies." (PMID 36589747, 2022). "Unexpectedly, our studies demonstrate that neither mTOR nor GSK3 inhibitors disturb the expression of P2X7R in neuroblastoma cells, indicating that non-canonical downstream effectors of Akt, or even directly Akt, should be implicated in the transcriptional regulation of P2rx7 gene." (PMID 26687764, 2015). "Previously we identified specificity protein 1 (Sp1) as the main factor involved in the transcriptional regulation of P2rx7 gene, reporting that serum withdrawal triggers the expression of P2X7R in Neuro-2a (N2a) neuroblastoma cell line." (PMID 26687764, 2015). "Both these studies demonstrated that a 24 h exposure to BCI significantly enhanced the levels of P2RX7, suggesting that a DUSP1/6-dependent mechanism may be involved in the upregulation of this receptor in neuroblastoma cells." (PMID 36589747, 2022). "We have also provided evidences that atypical PKCζ is playing a relevant role in the regulation of P2rx7 gene expression in neuroblastoma cells lacking trophic support." (PMID 26687764, 2015).
epilepsy (32 papers, 2010 to 2026). A brain disorder characterized by episodes of abnormally increased neuronal discharge resulting in transient episodes of sensory or motor neurological dysfunction, or psychic dysfunction. "Thus, we hypothesize that the microRNA-211-5p/P2RX7/ERK/GPX4 axis might regulate epilepsy-associated neuronal ferroptosis and oxidative stress." (PMID 38191407, 2024). "In fact, a recent study has shown increased P2X7R currents in GABAergic interneurons in epilepsy in mice and increased P2rx7 mRNA levels in neurons in TLE patients." (PMID 39886340, 2025). "In our study, P2RX7 blockade regulated GPX4/HO-1 by suppressing the ERK cascade in murine models of epilepsy." (PMID 38191407, 2024). "To illustrate potential signaling pathways through which P2RX7 mediates ferroptosis and alleviates epilepsy, we conducted transcriptome sequencing analysis and identified significant changes in the mitogen-activated protein kinase (MAPK) cascade." (PMID 38191407, 2024). "Taken together, these results obtained from the epilepsy mouse model are consistent with those obtained in vitro, emphasizing that P2RX7 alleviates seizures by inhibiting neuronal ferroptosis." (PMID 38191407, 2024). "In this research, we identified multiple mechanisms of ferroptosis in the pathogenesis of epilepsy and clarified that miR-211-5p accounts for the increase in P2RX7." (PMID 38191407, 2024). "In our study, the upregulation of P2RX7 in epilepsy was attributed to the downregulation of microRNA (miR)-211-5p." (PMID 38191407, 2024). "Further evidence supporting a role for P2X7R during epilepsy development stems from a study where mice were treated with inhibitors against microRNA-22, previously shown to target P2rx7 mRNA." (PMID 36982485, 2023). "It is still unclear whether there is a regulatory relationship between P2RX7 and ferroptosis, and whether they affect the progression of epilepsy." (PMID 38191407, 2024). "These bioinformatic and experimental results indicate that P2RX7 may primarily play a role in excitatory neurons in an epilepsy model." (PMID 38191407, 2024). "Moreover, we found that the upregulation of P2RX7 in epilepsy was attributed to the downregulation of microRNA-211-5p in the preliminary bioinformatics analysis and experiments of this study." (PMID 38191407, 2024). "In our study, we showed that the expression of P2RX7 was significantly increased in epilepsy." (PMID 38191407, 2024). "The regulation of the MAPK signaling pathway by P2RX7 in epilepsy was confirmed in our experiments." (PMID 38191407, 2024). "P2RX7 was expressed predominantly in excitatory neurons in epilepsy." (PMID 38191407, 2024). "Thus, we hypothesized that the upregulation of P2RX7 in epilepsy was attributed to the downregulation of microRNA-211-5p." (PMID 38191407, 2024). "Therefore, we hypothesized that the upregulation of P2RX7 in epilepsy was attributed to the downregulation of miR-211-5p." (PMID 38191407, 2024). "In contrast, P2RX7 and TMTC2 presented a trend opposite that of miR-211-5p, so we only focused on these upregulated genes in epilepsy." (PMID 38191407, 2024). "However, the exact reasons for the upregulation of P2RX7 expression in epilepsy are not fully understood, but several hypotheses and mechanisms can explain this phenomenon, such as high ATP release, increased intracellular calcium levels, elevated levels of inflammation and regulation by microRNAs." (PMID 38191407, 2024). "Ultimately, 5 target genes were obtained, of which P2RX7 and TMTC2 were upregulated and CACNA1C, JPH3 and GRM1 were downregulated in epilepsy." (PMID 38191407, 2024). "By using P2rx7-GFP reporter mice, our group has also now determined cell-specific patterns of P2rx7 transcription during epilepsy." (PMID 28210205, 2017). "While it is possible that miR-211-5p may also affect epilepsy by targeting TMTC2, our current study primarily assessed P2RX7, which displayed the most significant upregulation as measured by qRT-PCR." (PMID 38191407, 2024).
epilepsy (continued). "Furthermore, we confirmed that P2RX7 is a novel regulator that inhibits ferroptosis by regulating the MAPK/ERK signaling pathway during the development and progression of epilepsy." (PMID 38191407, 2024). "Thus, blocking P2RX7 might regulate GPX4/HO-1 axis by suppressing the MAPK-ERK pathway, participating in ferroptosis in epilepsy." (PMID 38191407, 2024). "This could be teased apart in future studies, for example, by studying the development and progression of epilepsy in mice lacking P2rx7 in different cell types." (PMID 38259288, 2023).
glioma (30 papers, 2012 to 2025). A benign or malignant brain and spinal cord tumor that arises from glial cells (astrocytes, oligodendrocytes, ependymal cells). "Subsequent studies have shown the association between P2RX7 inhibition and the reduction of tumor enlargement within gliomas." (PMID 37241023, 2023). "The P2RX7 gene has been recently identified as a susceptibility gene for glioma in dogs, but the picture is as yet unclear in humans." (PMID 31448051, 2019). "The non-synonymous canine SNV associated with glioma in this study has recently been shown to result in approximately 50% decrease in P2RX7 function, and non-synonymous SNPs in P2RX7 have been identified in an increasing number of human patients with a variety of conditions including cancer." (PMID 27171399, 2016). "We then verified whether U138-wt glioma cells might have P2RX7 loss-of-function SNPs." (PMID 31448051, 2019). "Reduced P2RX7 expression resulted in the development of various cancers and P2RX7 inhibition by shRNA in glioma tissue increased EGF and phosphor-EGF protein expression." (PMID 36741002, 2023). "Together, our results support a previously hypothesized role for P2RX7 in glioma tumorigenicity where truncated P2RX7 isoforms in the ATP-enriched tumor microenvironment are tonically active without leading to cytotoxic pore formation." (PMID 41400763, 2025). "However, further research is needed on the impact that gliomas have on the P2X ligand channel, as the unique changes that GBMs and other gliomas induce on P2RX7 are a potential therapeutic target for tumor progression." (PMID 37241023, 2023). "It has been shown that GBMs and gliomas show strong upregulation of P2RX7." (PMID 37241023, 2023). "Similarly, the genes with increased copy numbers, such as CD4, PIK3CA, and P2RX7, had higher expression levels in glioma, indicating a positive correlation of CNVs with the expression levels of ICD-related genes." (PMID 36428756, 2022). "A locus on canine chromosome (CFA) 26 has been strongly associated with glioma risk across multiple dog breeds, with regional mapping revealing single nucleotide variants in three neighboring genes DENR, CAMKK2, and P2RX7 that are highly associated with glioma susceptibility." (PMID 31788444, 2019). "However, the role of P2RX7 in glioma is complex and expression has been shown to result in both suppression and an increase in glioma growth in a variety of models, suggesting additional effects beyond immune surveillance." (PMID 27171399, 2016). "In addition to the higher P2RX7 mRNA levels that we detected in dog glioma, we report an intriguing pattern of differently sized proteins occurring between tumor and non-tumor dog brain." (PMID 27171399, 2016). "In human colon tumor HCT-8 and Caco-2 cell lines or in glioma cell line GL261, the activation of P2RX7 could inhibit tumor cell proliferation." (PMID 41007849, 2025). "P2RX7 protein expression was assessed in matched and unmatched normal cerebrum and tumors by western blotting and was detected in all canine normal brain samples and in 16/17 glioma samples." (PMID 27171399, 2016).
diabetes (29 papers, 2008 to 2025). "In vitro systems mimicking diabetes through high glucose exposure have shown that the P2rx7 pathway is closely associated with ATP-induced cell death in human primary fibroblasts." (PMID 31035433, 2019). "We found that the expression of P2rx7 was increased in the murine retina as early as one month following diabetes induction." (PMID 31035433, 2019). "Diabetes has been shown to upregulate P2rx7 expression in various cells, and in the current study, we demonstrated that expression of this receptor was increased in the diabetic retina." (PMID 31035433, 2019). "With ERG data suggesting that P2rx7 inhibition was protective against diabetes-induced retinal neuronal damage, further post-mortem analysis was conducted to understand which neuronal populations were protected by 3TC." (PMID 31035433, 2019). "Diabetes-related hyperglycaemia and hyperlipidaemia have been shown to upregulate P2rx7 expression or activity in skin fibroblasts in patients, while this receptor is also increased in the pancreatic α-cells, macrophages, kidneys, and corneas of mice with streptozotocin (STZ)-induced diabetes." (PMID 31035433, 2019). "Within the eyes, P2rx7 has been reported to be specifically expressed in retinal neurons under normal physiological conditions, although precisely how this receptor system is regulated in the retina during diabetes remains unknown." (PMID 31035433, 2019). "Diabetes-induced renal inflammatory pathology has been shown to be attenuated in mice lacking P2rx7." (PMID 31035433, 2019). "Despite accruing evidence suggesting a possible role for P2rx7 in diabetes-related cell pathology, this pathway has not been extensively studied in DR." (PMID 31035433, 2019).
melanoma (29 papers, 2014 to 2025). A malignant, usually aggressive tumor composed of atypical, neoplastic melanocytes. "Nonetheless, the Human Protein Atlas and The Cancer Genome Atlas report a trend for P2RX7 enrichment at both transcript and protein levels in skin and melanoma tissues, and worse clinical outcomes are associated with a high expression." (PMID 39001489, 2024). "For example, glyburide, a compound investigated in the setting of gestational diabetes mellitus, or P2RX7 inhibitors, which were shown to exert an antitumor effect in murine melanoma models, are known to inhibit potassium efflux." (PMID 38397043, 2024). "Furthermore, extracellular ATP, via P2RX7 signaling, enhances the aggressiveness of vemurafenib-resistant melanoma cells." (PMID 41469519, 2025). "Increased P2RX7 levels are reported in human melanoma and in several melanoma cell lines." (PMID 35933451, 2022). "Moreover, this possible relationship may be reflected in the relatively high but wide range of P2RX7 transcript abundance in melanoma compared to other tumor types." (PMID 39001489, 2024). "We have shown that activation of P2RX7 using a positive modulator (HEI3090) inhibits tumor growth in lung and melanoma mouse models." (PMID 37298187, 2023). "The use of P2X7 targeted small molecule inhibitors and P2RX7 genetic knock out in a murine melanoma model leads to modulation of CD39 and CD73 expression levels on several immune cell populations including Tregs, CD4+ effector lymphocytes, macrophage and DCs." (PMID 32581786, 2020). "Potassium efflux can be inhibited by glyburide, a compound tested in gestational diabetes mellitus or by P2RX7 inhibitors (oxATP, AZ10606120), which have shown anti-tumor effects in the murine B16 melanoma model." (PMID 32635472, 2020). "Indeed, studies using tumor cell lines and preclinical mouse models in melanoma, non-melanoma skin cancers, intestinal carcinomas and breast cancer have shown that activation of P2RX7 reduced cell proliferation by inducing cell death." (PMID 37298187, 2023). "Indeed, activation of the P2RX7/IL-18 axis with HEI3090 sensitized lung and melanoma tumors to immunotherapy, cured 80% of mice and protected them from a tumor rechallenge, highlighting the potency of IL-18 in generating long lasting memory T cells in tumor models." (PMID 37298187, 2023).
rheumatoid arthritis (26 papers, 2012 to 2026). A chronic, systemic autoimmune disorder characterized by inflammation in the synovial membranes and articular surfaces. "Notably, some P2RX7 SNPs are associated with various infectious, inflammatory and autoimmune diseases, such as tuberculosis, sepsis, multiple sclerosis (MS) and rheumatoid arthritis (RA)." (PMID 35883539, 2022). "P2RX7 inhibitors were tested in systemic autoimmune/inflammatory diseases such as rheumatoid arthritis and Crohn’s disease." (PMID 40371642, 2025). "In the context of rheumatoid arthritis, there have been several clinical trials using P2RX7 antagonists as a means of reducing inflammation." (PMID 30949163, 2019).
lung carcinoma (25 papers, 2014 to 2025). "However, P2RX1, P2RX7, P2RY12, P2RY13, and P2RY14 were relatively downregulated in lung cancer tissues and were associated with a favourable prognosis." (PMID 33501930, 2021). "However, in our data, we found that P2RX7 was downregulated and was a good prognostic factor in lung cancer." (PMID 32638267, 2020). "However, purinergic receptors P2RX1, P2RX7, P2RY12, P2RY13, and P2RY14 were relatively downregulated in lung cancer tissues and were associated with favorable prognosis." (PMID 32638267, 2020). "Although we showed that HEI3090 enhances IL-18 release in vivo, it is of interest to study its impact on P2RX7 activation in vivo, especially since HEI3090 is a promising molecule for treatment of lung cancer." (PMID 36600200, 2023). "We also showed that contrast with the unfavorable prognosis of pyrimidine metabolic rate–limiting enzymes, purinergic receptors P2RX1, P2RX2, P2RX7, P2RY12, P2RY13, and P2RY14 were favorable prognostic markers in patients with lung cancer." (PMID 32638267, 2020). "created a novel Lung cancer prediction model that integrates 5 PyMGs, including P2RX1, P2RX7, P2RY12, P2RY13, and P2RY14, which might be utilized to predict prognosis in Lung cancerpatients." (PMID 37664033, 2023). "High expression of the BC-specific ICD-derived metagene signature (TNF/CXCR3/P2RX7/CASP1/NLRP3/IL1B/LY96/CD4+/CD8+A/CD8+B/PRF1/IFNG/IL17A/IL17RA) is associated with prolonged overall survival (OS) in BC and OC patients but not in lung cancer patients." (PMID 37445860, 2023). "We only identified 4 studies when we entered “lung cancer” and “suramin” as keywords across the 24 nonselective and selective inhibitors targeting P2RX7." (PMID 35454832, 2022).